APOA1 (apolipoprotein A1)
Diseases named in the same sentence as APOA1 in open-access papers (continued):
Sharing a sentence is not in itself a finding about the gene and the disease.
osteoporosis (9 papers, 2022 to 2026). A condition of reduced bone mass, with decreased cortical thickness and a decrease in the number and size of the trabeculae of cancellous bone (but normal chemical composition), resulting in increased fracture incidence. "It was also shown that participants with higher apolipoprotein A1 levels had a 71.2% greater risk of developing osteoporosis than those with lower apolipoprotein A1 levels, and for each one-unit increase in apolipoprotein A1, the risk was 1.29 times greater." (PMID 38831414, 2024). "The results showed that the risk of osteoporosis significantly decreased with the increase of APOA1." (PMID 37396919, 2023). "Unfortunately, because our study was the first report of an association between ApoA1 and osteoporosis, we were unable to perform a comparative analysis with similar studies." (PMID 36864426, 2023). "Higher levels of apolipoprotein A1 (ApoA1) were associated with higher risk of osteoporosis, which supports the argument that lipid metabolism is involved in bone metabolism." (PMID 36864426, 2023). "Multivariate logistic regression analysis, sensitivity analysis, and receiver operator characteristic (ROC) were used to assess the association of ApoA1 with osteoporosis." (PMID 36864426, 2023). "Nevertheless, our study not only found HDL-C to be associated with osteoporosis, but also found that higher levels of ApoA1 were independently associated with a higher risk of osteoporosis." (PMID 36864426, 2023). "Although we found for the first time that higher levels of ApoA1, which has cardiovascular benefits, were strongly associated with a higher risk of osteoporosis, there were still some limitations to our study." (PMID 36864426, 2023). "A significant association between osteoporosis and APOA1 was also observed after additional adjustment for HbA1c, TG, HDL-c, APOA1, LDL-c, creatinine, ALT, UA, and HOMA-IR (model 2), and the ORs (95%CI) was 0.843 (0.782–0.910) respectively." (PMID 37396919, 2023). "Additionally, it has been demonstrated that APOA1 is independently linked to a decreased risk of osteoporosis." (PMID 37970652, 2024). "Therefore, to fill this knowledge gap, the present study aimed to explore the association of ApoA1 with osteoporosis in the general population in a large cross-sectional study." (PMID 36864426, 2023). "Although the current evidence shows that lipid metabolism and osteoporosis are closely related to cardiovascular disease, the association between ApoA1 and osteoporosis is still unknown." (PMID 36864426, 2023). "And whether ApoA1 was a continuous variable or a categorical variable, higher ApoA1 was consistently associated with a higher risk of osteoporosis after excluding individuals with gout and adjusting for confounding variables (All P < 0.01)." (PMID 36864426, 2023). "Furthermore, APOA1 is also shown to be independently associated with lower odds of osteoporosis." (PMID 37396919, 2023). "In addition, APOA1 is also shown to be independently associated with lower odds of osteoporosis." (PMID 37396919, 2023). "This is in line with other studies that reported that ApoA1 was positively correlated with vitamin D in Korean cohorts and in Chinese osteoporosis patients." (PMID 40613069, 2025). "The results showed that the relationship between ApoA1 and osteoporosis remained stable after excluding individuals with gout." (PMID 36864426, 2023). "APOA1 is also shown to be independently correlated with osteoporosis after adjustment for confounding factors, and the OR (95%CI) was 0.851 (0.784–0.924)." (PMID 37396919, 2023). "Third, APOA1 seemed to have a more significant identifying value of osteoporosis than other serum lipids, and more studies with enough follow-up to confirm these findings." (PMID 37396919, 2023). "Participants with higher ApoA1 had higher rates of osteoporosis compared to participants with lower ApoA1 (P < 0.05)." (PMID 36864426, 2023).
osteoporosis (continued). "A study carried out by Blair’s research groups in ApoA-1−/− deficiency mice proved that the elimination of ApoA-1, the prominent component of HDL, leads to severe osteoporosis." (PMID 36498945, 2022). "Therefore, the purpose of this study was to explore the relationship between ApoA1 and osteoporosis." (PMID 36864426, 2023). "The AUC (95% CI) of APOA1 identifying osteoporosis was 0.615 (0.577–0.652)." (PMID 37396919, 2023). "And ROC analysis also showed that ApoA1 could predict the development of osteoporosis (AUC = 0.650, P < 0.001)." (PMID 36864426, 2023). "ApoA1 was regarded as an exposure variable and osteoporosis was considered as an outcome variable." (PMID 36864426, 2023). "The AUC (95% CI) of APOA1 in identifying osteoporosis was 0.615 (0.577–0.652)." (PMID 37396919, 2023). "Third, because all participants were from the US population only, the relationship between ApoA1 and osteoporosis in other countries is still unknown." (PMID 36864426, 2023). "Furthermore, APOA1 seemed to have the largest areas under the curve (AUC) for osteoporosis." (PMID 37396919, 2023). "Additionally, the potential pathological mechanism between ApoA1 and osteoporosis is unknown, and more basic and clinical studies are needed to further explore the mystery." (PMID 36864426, 2023). "First, the causal relationship between ApoA1 and osteoporosis could not be determined because of the limitations of the observational study." (PMID 36864426, 2023). "Furthermore, APOA1 has a more considerable osteoporosis-identifying value than other serum lipids." (PMID 37396919, 2023). "This study aimed to elucidate the correlation between APOA1 levels and lumbar BMD in patients with osteoporotic fracture (OPF) for novel insights into potential therapeutic strategies against osteoporosis." (PMID 39144661, 2024). "The results displayed a decreasing trend in the prevalence of osteoporosis across the HDL-c and APOA1 tertiles (p < 0.05)." (PMID 37396919, 2023). "ROC analysis showed that ApoA1 could predict the occurrence of osteoporosis (AUC = 0.650, P < 0.001), and we divided all participants into two groups according to the optimal cutoff point of ApoA1 obtained by ROC: lower ApoA1 group (ApoA1 ≤ 1.36 g/L) and higher ApoA1 group (ApoA1 > 1.36 g/L)." (PMID 36864426, 2023). "In this cross-sectional study, we found for the first time a close association between ApoA1 and osteoporosis, and the significance of this association was not changed by confounding factors, suggesting that ApoA1 or lipid metabolism may be involved in the occurrence and development of osteoporosis." (PMID 36864426, 2023). "Furthermore, APOA1 is also shown to be independently correlated with L1-L4 BMD and lower odds of osteoporosis." (PMID 37396919, 2023). "APOA1 is independently associated with OC, L1-L4 BMD, and osteoporosis rather than HDL-c in Chinese postmenopausal women with T2DM." (PMID 37396919, 2023). "Individuals with osteoporosis had higher levels of ApoA1 than individuals without osteoporosis (P < 0.05)." (PMID 36864426, 2023).
polycystic ovary syndrome (9 papers, 2014 to 2024). A disorder that manifests as multiple cysts on the ovaries. "There was a difference when stratifying according to hyperandrogenemia, with APCS, ApoE and ApoA1 higher in hyperandrogenemia (p < 0.01, p < 0.04 and p < 0.01, respectively), while PAPPA was decreased in hyperandrogenemia (p < 0.01)." (PMID 38256230, 2024). "Women with polycystic ovarian syndrome exhibited lower levels of apolipoprotein A1 than did normal women." (PMID 35417047, 2022). "This study was a secondary analysis of the Acupuncture and Clomiphene for Chinese Women with Polycystic Ovary Syndrome trial (PCOSAct), and 957 subjects with available ApoB and ApoA1 measurements were included." (PMID 35069437, 2021). "The Chinese study demonstrated that the ratio of apolipoprotein B to apolipoprotein A1 is a good predictive indicator of MetS and pre-MetS in young women with polycystic ovary syndrome." (PMID 32668760, 2020). "ApoA1 protein was also evidenced by Western blot in the GC of healthy and polycystic ovary syndrome patients." (PMID 30347829, 2018). "This is also in line with other studies which have shown that APOA1 levels are reduced in women with polycystic ovary syndrome (PCOS), which has an increased prevalence in ASC relative to the general population." (PMID 24467795, 2014). "When stratified according to demographic parameters, hyperandrogenemia showed increased APCS, ApoE and ApoA1, whereas PAPPA was decreased." (PMID 38256230, 2024).
prediabetes (9 papers, 2011 to 2024). "The present results are highly consistent with a study conducted in China that showed a strong association between the mean ApoB/ApoA1 ratio and prediabetes." (PMID 39081429, 2024). "However, to our current understanding, there have been limited studies that have identified an independent association between the ApoB/ApoA1 ratio and lipoprotein ratio with glycemic levels in individuals with prediabetes." (PMID 39081429, 2024). "Individuals with prediabetes exhibited significantly higher mean levels of Lp(a), mean ApoB/ApoA1 ratio, and mean LDL-C/HDL-C ratio compared to apparently healthy individuals." (PMID 39081429, 2024). "A strong correlation was found between the ApoB/ApoA1 ratio and glycemic levels in individuals with prediabetes." (PMID 39081429, 2024). "Consequently, the objective of this study is to evaluate the ApoB/ApoA1 ratio and LDL-C/HDL-C ratio in prediabetes in relation to glycemic levels and establish the association between apolipoprotein and lipoprotein ratios in prediabetic individuals and their glycemic levels." (PMID 39081429, 2024). "There was a significant high mean level of Lp(a), mean ApoB/ApoA1 ratio, and mean LDL-C/HDL-C ratio in individuals with prediabetes compared to apparently healthy individuals." (PMID 39081429, 2024).
pulmonary hypertension (9 papers, 2016 to 2023). Increased pressure within the pulmonary circulation due to lung or heart disorder. "Furthermore, administration of a peptide mimetic of ApoA-1 reduced pulmonary hypertension in rodent models with PH." (PMID 36902298, 2023). "It has also been reported that levels of ApoA1, the major protein component of HDL, were decreased in SCD and that patients with the lowest ApoA1 levels had blunted flow-mediated dilation in response to acetylcholine and had higher prevalence of pulmonary hypertension." (PMID 36422126, 2022).
rectal cancer (9 papers, 2015 to 2025). A primary or metastatic malignant neoplasm that affects the rectum. "A study found that the APOB/APOA1 ratio is a specific predictor of liver metastasis in rectal cancer patients." (PMID 38067270, 2023). "We identified and confirmed a 10-protein panel for nCRT response prediction and four potential biomarkers HEP2, GELS, S10A8 and APOA1 for prognosis of rectal cancer based on iTRAQ-based comparative proteomics screening and PRM-based targeted proteomic validation." (PMID 35945555, 2022). "In addition, elevated serum ApoB/ApoA1 level predicts a poorer survival in patients with metastatic CRC and also a higher risk of liver metastasis in patients with locally advanced rectal cancer." (PMID 36506554, 2022). "Although, another study which assessed this prognostic factor found that a high APOB/APOA1 ratio was found to predict poorer survival in patients with metastatic CRC to the liver, as well as in patients with advanced rectal cancer." (PMID 38067270, 2023). "In this work, we demonstrated that APOA1 and PEDF in post-nCRT sera were correlated with DFS of rectal cancer." (PMID 35945555, 2022). "A negative correlation is found between serum ApoA1 and the response to neoadjuvant chemoradiotherapy in patients with rectal cancer." (PMID 36506554, 2022).
coronary stenosis (8 papers, 2015 to 2025). Narrowing of the coronary artery lumen diameter. "The mutation at PCSK6 rs1531817 increased the ApoA1/ApoB ratio, which in turn protected against severe coronary stenosis." (PMID 39039525, 2024). "Our study also found that lipid ratios such as the ApoB/ApoA-1 ratio (BAR) were closely associated with the degree of coronary artery stenosis and might have a potential predictive value for CHD severity." (PMID 40129766, 2025). "Patients with the PCSK6 CA + AA genotype have milder coronary stenosis and a better long-term prognosis; according to the mediation model, ApoA1/ApoB and TC/HDL partially mediate." (PMID 39039525, 2024). "PMI patients with the PCSK6 CA + AA genotype have milder coronary stenosis, partially because they have higher ApoA1/ApoB levels; patients with the PCSK6 CA + AA genotype have a better long-term prognosis, partially because they have lower TC/HDL levels and are less likely to have TVD." (PMID 39039525, 2024). "For the first time, the significant positive correlation between HDL-C and APOA1 expression and negative correlations of HDL-C and transcripts of ten HDL-related genes and eleven atherogenesis-prone genes even at the absence of morphologically evident coronary stenosis were revealed." (PMID 33269026, 2020).
leukemia (8 papers, 2013 to 2025). A malignant (clonal) hematologic disorder, involving hematopoietic stem cells and characterized by the presence of primitive or atypical myeloid or lymphoid cells in the bone marrow and the blood. "Of note, APOA1 appeared previously to discriminate between LR and HR leukemias as well as between normal and aberrant karyotype." (PMID 23849470, 2013). "Proteins Clus, Ceru, ApoE, ApoA4, ApoA1, Gels, S10A9, Ambp, Actb, Cata and Afam have an important role in leukaemia prognosis, mainly as distinctive signals for aggressive leukaemia cases." (PMID 25537633, 2015). "APOA1, the major protein component of high-density lipoprotein (HDL) was up-regulated in both LR- and HR-leukemias, verifying a lipid metabolic derangement of HDL." (PMID 23849470, 2013). "However, low ApoA1 level did not influence leukemia-free survival (LFS, P = 0.367)." (PMID 35100989, 2022).
myopia (8 papers, 2008 to 2025). "APOA1 has emerged as a significant protein in several studies, associated with myopia arrest in animal models 87 and identified in both chick embryo vitreous 38 and AH exosomes of HM patients." (PMID 39430251, 2024). "Future studies should further investigate the role of APOA1 in pathological myopia and establish a foundation for developing new treatment strategies." (PMID 41315216, 2025). "Western blot validated apolipoprotein A1 and ovotransferrin as potential myopia markers in ocular development." (PMID 28978931, 2017). "Such expression changes were evident, particularly in the late myopia dataset where a wide range of genes linked with oxidative stress were either up-regulated (GPX1, GSTA3, MT-4, APOA1, OTUB, PTGDS, HSPB1, HSPB2) or down-regulated (XHD, SLC40A1, TF, SOD3, HPGDS, BCMO1)." (PMID 28852117, 2017). "In pathological myopia, the upregulation of APOA1 expression may be limited by various factors." (PMID 41315216, 2025). "More recently, apolipoprotein A1 in chick choroid and sclera were found to have a novel regulatory feedback mechanism with retinoic acid, a well-established signal for regulating eye growth in myopia, in a concentration-dependent manner to control postnatal ocular growth." (PMID 28978931, 2017). "More interestingly, we found that two of them, apolipoprotein A1 (APOA1) and opticin (OPTC), commonly had high expression in either myopia or control patients." (PMID 33850473, 2021). "Notably, APOA1 is recognized as a “STOP” signal that slows myopia progression by inhibiting axial overgrowth and may also play a role in the transport of retinoic acid (RA) from the choroid to the sclera, which inhibits scleral proteoglycan synthesis and prevents myopia development." (PMID 41315216, 2025).
nonalcoholic fatty liver disease (8 papers, 2020 to 2025). "CagA+ strains disrupt lipid metabolism, increasing non-alcoholic fatty liver disease, cardiovascular, and Alzheimer’s risks via PPAR interference, GBA1 demethylation, and altered FABP1/APOA1 expression, reversible by eradication." (PMID 41158522, 2025).
pneumonia (8 papers, 2016 to 2024). An acute, acute and chronic, or chronic inflammation focally or diffusely affecting the lung parenchyma, caused by an infection in one or both of the lungs (by bacteria, viruses, fungi, or mycoplasma.). "The results revealed that LDH > 289 U/mL and ApoA1 < 0.92 mg/mL would increase the risk of death from severe pneumonia, with statistically significant differences (OR=4.275, 0.548, P<0.05)." (PMID 38699695, 2024). "The study suggests that LDH > 289 U/mL and ApoA1 < 0.92 mg/mL are independent risk factors for severe pneumonia." (PMID 38699695, 2024). "It was also known that in severe pneumonia the haptoglobin increase was associated to the apolipoprotein-A1 decrease, as we observed in the cohorts with high prevalence of severe Covid-19." (PMID 33216772, 2020). "In patients with severe pneumonia, apolipoprotein-A1 decrease was associated with acute inflammation and the “cytokine storm” with an increase in IL6 and acute phase proteins such as CRP and haptoglobin." (PMID 33216772, 2020). "The study found that ApoA1 levels may be associated with the onset and severity of severe pneumonia." (PMID 38699695, 2024). "ApoA1 is closely correlated with the progression of pneumonia disease, and decreased expression may cause an increase in the expression of pro-inflammatory factors, which in turn decreases the ability of lung tissue to resist pathogens and further exacerbates the inflammatory response." (PMID 38699695, 2024). "ApoA1 predicted death in patients with severe pneumonia with an AUC of 0.754 (95% CI (0.616~0.891)) and a cut-off value of 0.92 mg/mL with a sensitivity of 72.2% and specificity of 73.1%." (PMID 38699695, 2024). "The differences in LDH and ApoA1 levels were statistically significant (P<0.05) when comparing patients with severe pneumonia with different PSI grades or APACHE II scores." (PMID 38699695, 2024). "Quantitative analysis of ApoA1 can provide an assessment of the inflammatory response in patients with severe pneumonia." (PMID 38699695, 2024). "The differences in LDH and ApoA1 levels were statistically significant when comparing patients with severe pneumonia at different ages (P<0.05)." (PMID 38699695, 2024). "In conclusion, elevated LDH levels and reduced ApoA1 levels in patients with severe pneumonia are valuable in assessing patients' conditions and prognosis, and can provide assistance in the early assessment of patients' conditions and diagnosis and treatment." (PMID 38699695, 2024). "LDH and ApoA1 levels in patients with severe pneumonia with different duration of mechanical ventilation were compared with statistically significant differences (P<0.05)." (PMID 38699695, 2024). "The AUC of LDH combined with ApoA1 to predict death in patients with severe pneumonia was 0.873 (95% CI (0.779 ~0.967)), with a higher area under the line than the test alone, sensitivity of 85.14% and specificity of 82.83%." (PMID 38699695, 2024). "The differences in LDH and ApoA1 levels were statistically significant (P<0.05) when comparing patients with severe pneumonia with different ICU length of stay." (PMID 38699695, 2024). "Severe pneumonia triggers an inflammatory response, leading to changes in ApoA1 expression levels." (PMID 38699695, 2024). "LDH and ApoA1 are clinically accessible, often repeatedly tested, quick and easy indicators, which are more ideal clinical markers of catabolic status in patients with severe pneumonia and can be easily promoted in primary hospitals." (PMID 38699695, 2024). "Therefore, the use of LDH and ApoA1 to predict the condition and prognosis of patients with severe pneumonia has some clinical value." (PMID 38699695, 2024). "Therefore, this study aimed to investigate the potential value of LDH and apolipoprotein A1 levels in diagnosis, assessment of disease severity, and prediction of prognosis in patients with severe pneumonia." (PMID 38699695, 2024).